CKS2 (CDC28 protein kinase regulatory subunit 2)
Description:
Binds to the catalytic subunit of the cyclin dependent kinases and is essential for their biological function.
Synonyms: CKSHS2
Tractability: Small molecule: a structure with a bound ligand is known; it has a high-quality binding pocket. PROTAC: ubiquitination databases record sites on it.
Target class: Kinase; Protein kinase regulatory subunit; Enzyme
Gene: Protein-coding gene on chromosome 9 (89,311,155 to 89,316,715, forward strand). Ensembl gene ENSG00000123975.
Subcellular location (Human Protein Atlas): Cytosol; Mitochondria; Nucleoplasm; Vesicles
Gene Ontology:
Molecular function: protein binding; cyclin-dependent protein serine/threonine kinase activator activity; histone binding; protein kinase binding; ubiquitin binding; chromatin binding; cyclin-dependent protein serine/threonine kinase regulator activity
Biological process: regulation of mitotic cell cycle
Cellular component: cyclin-dependent protein kinase holoenzyme complex; SCF ubiquitin ligase complex
Genetic constraint (gnomAD): Loss-of-function variants: 4 observed, 11.7 expected, observed/expected ratio (o/e) 0.34, 90% interval 0.17 to 0.78. The upper end of that interval is the gene's LOEUF score, 0.78, which puts it in group 3 of 6, group 1 being the genes least tolerant of losing a copy. Missense variants: 55 observed, 72.54 expected, observed/expected ratio (o/e) 0.76, 90% interval 0.61 to 0.95. Synonymous variants: 28 observed, 21.07 expected, observed/expected ratio (o/e) 1.33, 90% interval 0.98 to 1.79.
Homologues: Orthologues: chimpanzee CKS2 (100% identical), macaque CKS2 (100% identical), pig CKS2 (100% identical), rabbit CKS2 (100% identical), dog CKS2 (99% identical), guinea pig CKS2 (99% identical), mouse Cks2 (99% identical), rat Cks2 (99% identical), rat Cks2l1 (90% identical), rat LOC120102505 (90% identical), zebrafish CKS2 (85% identical), Drosophila melanogaster Cks85A (63% identical), and 1 more. Paralogues in human: CKS1B (81% identical), NIP7 (32% identical).
Diseases named in the same sentence as CKS2 in open-access papers:
CKS2 is named in the same sentence as 76 diseases in open-access papers, as found by Europe PMC text mining. Sharing a sentence is not in itself a finding about the gene and the disease. The quoted sentences say what the papers report.
breast carcinoma (15 papers, 2016 to 2025). "Studies have found that CKS2 plays an important role in the development of bladder and prostate cancer, as well as breast cancer." (PMID 39188686, 2024). "Previous studies have shown that CKS2 is overexpressed in multiple tumors, such as esophageal cancer, breast cancer, and ovarian cancer 11-13." (PMID 34729099, 2021). "Cyclin-dependent kinases regulatory subunit 2 encoded by CKS2 is known to regulate in vitro tumorigenecity of tongue squamous cell carcinoma, ovarian, cancer, esophageal cancer, breast cancer, and hepatocellular carcinoma." (PMID 33669244, 2021). "The expressions of KIF4A, RACGAP1, CKS2, SHCBP1, and HMMR were high in breast cancer, associated with poor OS and different breast cancer subclasses." (PMID 33959662, 2021). "Of the key genes unique to basal-like breast cancer, the expression levels of only CDC7, KIF18A, STIL, and CKS2 were associated with patient survival time (P < 0.05)." (PMID 33066779, 2020). "The overexpression of CKS2 corresponds to metastasis and prognosis in various malignancies such as breast cancer, liver cancer and PCa (Yu, Zhong & Qiao, 2013)." (PMID 32266115, 2020). "We validated this strategy in vivo and observed that Cks2-overexpressing mammary tumors in nude mice were selectively sensitized to gemcitabine under conditions of methotrexate-induced replication stress." (PMID 29383129, 2017). "Furthermore, multiple lines of evidence suggest that CKS2 is abnormally expressed in several types of tumors, including esophageal cancer, breast cancer, and ovarian cancer, and is involved in tumor progression 11-13." (PMID 34729099, 2021). "Although rarely reported with MPM, there is accumulating evidence showing CKS2 is upregulated in many types of tumor as a prognostic factor, including hepatocellular carcinoma, colorectal cancer, bladder cancer, breast cancer, gastric cancer and epithelium ovarian cancer." (PMID 32849853, 2020). "Therefore, to extend our findings in a breast cancer model, we stably overexpressed Cks1 or Cks2 in MCF-7 human breast cancer cells, which intrinsically express low levels of CKS proteins." (PMID 29383129, 2017). "This concept was investigated in a mouse xenograft model where MCF-7 human breast cancer cells engineered to overexpress Cks2 were compared to their controls (with low Cks2 levels) for tumor growth responses after implantation into mammary fat pads of female nude mice." (PMID 29383129, 2017). "Moreover, a research with the observation that CKS2 level was increased in higher histopathological grade breast cancer led to the suggestion that CKS2 might exert a pivotal role in tumor cell motility." (PMID 36284444, 2023). "Elevated CKS2 expression has been documented in various cancers, including MLL‐rearranged leukemia, bladder cancer, and breast cancer." (PMID 39560180, 2024). "Previous research has indicated that CKS2 is significantly upregulated in tumors like NSCLC and breast cancer, serving as a potential biomarker for tumor diagnosis or treatment." (PMID 39548421, 2024). "For validation in UALCAN, GEPIA, and KM, 5 core genes (KIF4A, RACGAP1, CKS2, SHCBP1, and HMMR) were found to highly expressed in breast cancer tissues with poor prognosis." (PMID 33959662, 2021). "MCF-7 human breast cancer cells expressing intrinsically low levels of CKS proteins and Cks2-overexpressing derivatives were implanted into the mammary fat pads of female nude mice." (PMID 29383129, 2017). "These five genes (KIF4A, RACGAP1, CKS2, SHCBP1, and HMMR) could be potential targets for therapy in breast cancer and prediction of prognosis on the basis of bioinformatical analysis." (PMID 33959662, 2021). "First, although high expressions of KIF4A, RACGAP1, CKS2, SHCBP1, and HMMR were independent prognostic factors of poor OS of breast cancer, all the data in our research came from online database and we need further experiments in vitro and in vivo to validate our findings." (PMID 33959662, 2021).
breast carcinoma (continued). "CKS2, KIF4A, RACGAP1, and SHCBP1 all have positive correlation with HMMR; they may become combined indicator of prognosis or targets for different subtypes of breast cancer." (PMID 33959662, 2021).
hepatocellular carcinoma (13 papers, 2019 to 2024). A malignant tumor that arises from hepatocytes. "TCTP and CKS2 expression patterns are linked through the TCTP/CDC25C/CDK1 pathway, which was shown to be dysregulated in hepatocellular carcinoma." (PMID 40809150, 2024). "Meantime, CKS2 can promote the proliferation of hepatocellular cancer cells by down-regulating the expression of phosphatase and tensin homologues." (PMID 39188686, 2024). "In hepatocellular carcinoma, silencing CKS2 can significantly inhibit the proliferation, migration and invasion of cancer cells, induce the cell cycle to stop in G1 phase, and increase the apoptosis induced by common chemotherapy drugs." (PMID 39188686, 2024). "Increasing evidence suggests the oncogenic function of overexpressed CKS2 in various human cancers, including adrenocortical carcinoma, tongue squamous cell carcinoma, lung adenocarcinoma, and hepatocellular carcinoma." (PMID 35935749, 2022). "Another research on hepatocellular carcinoma unveiled the suppression of knocking down CKS2 expression on the migratory ability of hepatocellular carcinoma cells." (PMID 35693634, 2022). "The high expression of CKS2 is related with the progression of bladder cancer and hepatocellular carcinoma." (PMID 33083148, 2020). "Similarly, upregulated CKS2 was observed to facilitate the malignant phenotype of hepatocellular carcinoma." (PMID 35935749, 2022). "However, the clinical significance, oncogenic functions, and related mechanisms of CKS2 in hepatocellular carcinoma (HCC) remain largely unclear." (PMID 31781310, 2019). "In addition, CKS2 overexpression in hepatocellular carcinoma is significantly correlated with the aggressive clinical features and malignant behavior of HCC cells." (PMID 39188686, 2024).
colorectal cancer (10 papers, 2013 to 2024). A primary or metastatic malignant neoplasm that affects the colon or rectum. "Overexpression of CKS2 has been reported to be associated with several types of cancer, including colorectal cancer and cervical cancer." (PMID 35991567, 2022). "Additionally, studies in human colorectal cancer have linked elevated CKS2 expression to tumor progression and poor prognosis." (PMID 39560180, 2024). "Studies have shown that suppressing CKS2 expression leads to decreased cell viability, increased apoptosis, cell cycle arrest, and reduced cyclin expression in human colorectal cancer." (PMID 39560180, 2024). "The prognostic value of CKS2 has been discovered in multiple human cancers including adrenocortical carcinoma, lung adenocarcinoma, and colorectal cancer." (PMID 35693634, 2022). "In colorectal cancer cells, attenuation of CKS2 results in decreased cell viability, increased cell apoptosis and cell cycle arrest." (PMID 29760609, 2018). "In addition to participating in the regulation of gastric cancer, liver cancer and colorectal cancer, CKS2 also acts as an oncogene in pancreatic cancer and esophageal cancer." (PMID 39188686, 2024). "However, whether CKS2 is upregulated in colorectal cancer (CRC) remains unknown." (PMID 24137409, 2013).
cervical carcinoma (7 papers, 2019 to 2024). A carcinoma arising from either the exocervical squamous epithelium or the endocervical glandular epithelium. "In cervical cancer, high CKS2 expression is associated with the presence of lymph node metastasis at diagnosis and with poor survival after chemoradiotherapy." (PMID 39188686, 2024). "In summary, upregulated CKS2 is closely associated with the malignant clinical development of cervical cancer and might serve as a valuable therapeutic target in cervical cancer." (PMID 35935749, 2022). "Studies have shown that CKS2 is overexpressed in cervical cancer as an oncogene and is related to the clinical progression of cervical cancer." (PMID 39188686, 2024). "In cervical cancer patients, the drug resistance of those with high CKS2 expression is significantly higher than that of those with low CKS2 expression, but the exact mechanism is still unclear." (PMID 39188686, 2024). "It is also believed that the carcinogenic effect of CKS2 overexpression in cervical cancer is related to cell cycle and DNA replication." (PMID 39188686, 2024). "Lymph node metastasis is extremely common for cancer, and the high expression of CKS2 in esophageal, gastric and cervical cancer tissues is positively correlated with the incidence of lymphatic invasion." (PMID 39188686, 2024). "The remarkable high expression of CKS2 in cervical cancer and the ability of CKS2 overexpression to discriminate against cervical cancer and noncancer cervix tissues was revealed in most datasets." (PMID 35935749, 2022). "The oncogenic influence of CKS2 overexpression in cervical cancer is related to the cell cycle, DNA replication, and estrogen signaling pathways." (PMID 35935749, 2022). "Herein, taking advantage of massive genetics data from multicenter RNA-seq and microarrays, we were the first group to perform tissue microarrays for CKS2 in cervical cancer." (PMID 35935749, 2022). "Expression data from multilevels of inhouse tissue microarray, other public RNA-seq, and microarrays consistently supported the high expression of CKS2 in cervical cancer." (PMID 35935749, 2022). "Only two studies revealed the mitochondrial function of CKS2 in the aggressive development of chemo radioresistant cervical cancer and the adverse impact of CKS2 high expression on the progression-free survival of cervical cancer patients." (PMID 35935749, 2022). "Patients with cervical cancer in stage II from inhouse microarrays had significantly higher expression of CKS2, and CKS2 overexpression had an adverse impact on the disease-free survival status of cervical cancer patients in GSE44001." (PMID 35935749, 2022). "IHC staining pictures reflected moderate or high immunoreactivity of CKS2 in the cancer nests of cervical cancer samples." (PMID 35935749, 2022). "Apart from genetic mutation profile analysis, we also identified genes significantly related to CKS2 in cervical cancer and their functional enrichment." (PMID 35935749, 2022). "In light of the importance of CKS2 as a hallmark for a broad type of tumor, it is worth investigating the clinicopathological significance and molecular mechanism of CKS2 in cervical cancer." (PMID 35935749, 2022). "In summary, CKS2 was identified as being overexpressed in CKS2 and is concerned with the clinical progression of cervical cancer." (PMID 35935749, 2022). "The disease-free survival condition of cervical cancer patients (sampled from GSE44001) worsened in the group with CKS2 high expression compared to cervical cancer patients with low CKS2 expression (HR = 2.321, P = 0.013)." (PMID 35935749, 2022). "CKS2 in complex with SSPB1 regulates mitochondrion DNA replication in cervical cancer and can be indicative of chemoradioresistance." (PMID 36203433, 2022). "There is one precedent in history that excavated the potential mechanisms of the tumor-boosting activities of CKS2 in cervical cancer." (PMID 35935749, 2022).
cervical carcinoma (continued). "In addition, studies also believe that CKS2 can be used as a biomarker of drug resistance to radiotherapy and chemotherapy of cervical cancer." (PMID 39188686, 2024). "This suggests that CKS2 plays an important role in cervical cancer." (PMID 39188686, 2024). "The overexpression of CKS2 in cervical cancer was indicated in the forest plot of SMD." (PMID 35935749, 2022). "Moreover, CKS2 expression in cervical cancer patients diagnosed to be in clinical stage II (11.097 ± 1.700) was higher compared with that in cervical cancer patients with clinical stage I (8.258 ± 2.175) (P < 0.001)." (PMID 35935749, 2022). "This includes cervical cancer specimens from microarrays and RNA-seq datasets, which might account for the upregulation of CKS2 in cervical cancer." (PMID 35935749, 2022). "Therefore, we aimed to systematically appraise the clinicopathological significance and explore the molecular bases of CKS2 in cervical cancer." (PMID 35935749, 2022). "It was in line with the previous study that CKS2 promoted chemoresistance of cervical cancer." (PMID 31781310, 2019). "CKS2 might serve as a valuable therapeutic target in cervical cancer." (PMID 35935749, 2022). "Here, taking advantage of massive genetics data from multicenter microarrays and RNA-seq data, we evaluated the clinicopathological significance of CKS2 with large samples (980 cervical cancers accompanied by 422 noncancer specimens)." (PMID 35935749, 2022). "We were also the first to evaluate the clinical significance of CKS2 with large samples (980 cervical cancer cases and 422 noncancer cases)." (PMID 35935749, 2022). "CKS2 was significantly upregulated in 62 cervical cancer tissues in contrast to 62 noncancer tissues (P < 0.001) (9.677 ± 2.407; 3.629 ± 1.591)." (PMID 35935749, 2022). "The limitations of the present study were the lack of experimental validation of the functional roles of CKS2 in cervical cancer and the connections between CKS2 and other coexpressed genes, which should be warranted in future work." (PMID 35935749, 2022).
esophageal cancer (7 papers, 2019 to 2024). A primary or metastatic malignant neoplasm involving the esophagus. "Meanwhile, overexpression of CKS2 in esophageal cancer is associated with advanced clinical stage and poor survival." (PMID 39188686, 2024). "In addition, CKS2 mRNA expression in esophageal cancer tissues was significantly higher than that in normal tissues, and overexpression of CKS2 was associated with depth of tumor invasion, lymphatic vessel invasion, clinical stage, distant metastasis and poor prognosis." (PMID 39188686, 2024). "CKS2 expression levels are also significantly up-regulated in patients with esophageal cancer, liver cancer and adrenal cortical cancer, and abnormally high CKS2 expression is associated with poor prognosis of patients." (PMID 39188686, 2024). "Knockdown of LINC00657 can inhibit the expression of CKS2, thereby inhibiting the proliferation, migration and invasion of esophageal cancer cells and inducing cell apoptosis." (PMID 39188686, 2024). "For instance, CKS2 inhibition has been shown to suppress proliferation, migration, invasion, and induce apoptosis in esophageal cancer cell lines." (PMID 39560180, 2024). "CKS2 was previously recommended as a prognostic marker in colorectal, breast, gastric, and esophageal cancers." (PMID 31781310, 2019). "Studies have shown that CKS2 mRNA expression in esophageal cancer tissues is significantly higher than that in normal tissues, and overexpression of CKS2 is correlated with depth of tumor invasion, lymphatic vessel invasion, clinical stage, distant metastasis and poor prognosis." (PMID 39188686, 2024). "Moreover, in esophageal cancer patients with the same TNM stage, the expression level of CKS2 in tissues of patients with good prognosis is significantly lower than that of patients with poor prognosis." (PMID 39188686, 2024).
gastric cancer (7 papers, 2014 to 2024). A primary or metastatic malignant neoplasm involving the stomach. "Cell cycle regulatory protein CKS2 is culpable for advancement of gastric cancer, but this gene might be linked with pathogenesis of pituitary prolactinoma." (PMID 33709028, 2021). "Down-regulation of CKS2 in gastric cancer cells has been reported to decrease cell proliferation and increase caspase-3 activation and Bax expression." (PMID 39188686, 2024). "Studies have shown that the expression of CKS2 in gastric cancer tissues is higher than that in adjacent normal tissues through TCGA database analysis, and the expression of CKS2 protein in gastric cancer tissues is closely related to the depth of tumor invasion and lymph node metastasis." (PMID 39188686, 2024). "In addition, in gastric cancer, the expression of CKS2 in gastric cancer tissues is higher than that in adjacent normal tissues, and the expression of CKS2 protein in gastric cancer tissues is closely related to the depth of tumor invasion and lymph node metastasis." (PMID 39188686, 2024).